BRCA1 (BRCA1 DNA repair associated)
Diseases named in the same sentence as BRCA1 in open-access papers (continued):
Sharing a sentence is not in itself a finding about the gene and the disease.
ovarian carcinoma (continued). "Women who have inherited genetic mutations have substantially increased risk of ovarian cancer, with a lifetime risk that varies with the genetic defect (for BRCA1, 30%–60%, for BRCA2, 15%–30% and for hereditary non-polyposis colon cancer, 7%)." (PMID 23591842, 2013). "Additionally, EGFR expression was higher in normal tissues of BRCA1-mutated patients, and was further increased in cancer tissues; EGFR levels were also significantly elevated in ovarian cancer with promoter hypermethylation-mediated inactivation of BRCA1." (PMID 24321281, 2013). "Carriers of inherited mutations in BRCA1 and BRCA2 genes face a lifetime risk of ovarian cancer of 35–60% (average age of diagnosis 50 years) and 12–25% (average age of diagnosis 60 years) respectively, and also an elevated risk of fallopian tube and peritoneal carcinomas." (PMID 23536787, 2013). "However, known mutations in BRCA1/2 and mismatch repair (MMR) genes can only explain a small part of the familial aggregation of ovarian cancer (5–13%)." (PMID 23133607, 2012). "The identification of the two major hereditary breast/ovarian cancer genes, BRCA1 (17q21, MIM* 113705) in 1994 and BRCA2 (13q14, MIM* 600185) in 1995, led to a new era in the diagnosis of inherited high predisposition to breast and ovarian cancer." (PMID 23961350, 2012). "Pathogenic mutations in BRCA1 and BRCA2 confer high risks of breast and ovarian cancers." (PMID 22348646, 2012). "In this review we will focus on the structural basis by which the BRCA1 protein functions as a tumor suppressor, and highlight the importance of these studies to understanding the pathophysiology and clinical outcomes of breast and ovarian cancers." (PMID 22737296, 2012). "Negative family history was more frequent in ovarian cancer patients with 300T>G missense BRCA1 mutation than in truncating 5382insC mutation carriers (p = 0.0025)." (PMID 22395474, 2012). "Thus, generation of SKOV3 sub-cell lines with stable BRCA1 expression would further assist in understanding the effect of BRCA1 in human ovarian carcinoma." (PMID 22685544, 2012). "The purpose of our study was to establish the frequency and spectrum of BRCA1 gene mutations in Polish consecutive breast and ovarian cancer patients in two groups: with positive and negative family history of BRCA1-related cancers." (PMID 22395474, 2012). "We observed that in Polish population negative family history is more frequent in the group of ovarian cancer patients with 300T>G BRCA1 mutation than in 5382insC carriers." (PMID 22395474, 2012). "The purpose of our study was to establish the frequency of positive family history of cancer in a series of Polish consecutive breast and ovarian cancer patients in two groups, with and without the BRCA1 gene mutations." (PMID 22395474, 2012). "The prevalence of BRCA1/2 LRs was investigated in 48,456 patients with diverse clinical histories and ancestries, referred for clinical molecular testing for suspicion of hereditary breast and ovarian cancer." (PMID 22544547, 2012). "RAD51D should be included in genetic screening of ovarian cancer families that do not have BRCA1/BRCA2 mutations." (PMID 22415235, 2012). "Overall, of the 110 women who developed TNBC and were analyzed (63 with and 47 without family history of breast and ovarian cancers), 23 BRCA1 and 4 BRCA2 carriers were identified, giving a mutation prevalence of 24.5%." (PMID 23116406, 2012). "Olaparib has demonstrated single agent activity in breast or ovarian cancer patients with germline mutations in BRCA1/2; an over 40% response rate has been reported in patients with BRCA mutant ovarian cancer, especially in patients with platinum sensitive disease." (PMID 22401667, 2012). "In addition, approximately 10–15% of ovarian carcinomas occur in women with inherited mutations in BRCA1 and BRCA2, who have an estimated 20–50% lifetime risk of ovarian carcinoma." (PMID 22792303, 2012).
ovarian carcinoma (continued). "The most important high penetrance breast and ovarian cancer susceptibility genes are BRCA1 and BRCA2 but, in addition to breast and ovarian cancer, germline mutations in these genes also increase the risk of prostate cancer and in BRCA2 also of pancreatic cancer." (PMID 23176254, 2012). "Nevertheless, whole-genome CNV profiling of patients fulfilling criteria for hereditary breast and ovarian cancer, but without BRCA1/BRCA2 mutations, has not been reported." (PMID 22314128, 2012). "This suggests that, regardless of the TNBC status, in the absence of family history of breast or ovarian cancer in this age group, a low (<10%) probability exists of having a BRCA1 or BRCA2 mutation." (PMID 23116406, 2012). "As the BRCA1 mutation can be detected in 10–15% of unselected ovarian cancer cases, positive family history is not necessary to qualify the patient for genetic tests." (PMID 22395474, 2012). "In addition, we included the well-characterized isogenic Brca1 null and wild type (WT) cell lines in our study, because of the high incidence of BRCA1 dysfunction in ovarian cancer." (PMID 22531354, 2012). "Although there are no reports showing involvement of SMAD6 in ovarian cancer, the stimulation of SMAD6 by BRCA1 as observed in our study may be suggestive of cytoprotective role of SMAD6 in ovarian cancer, and thus needs further investigation." (PMID 22685544, 2012). "In ovarian cancer patients, negative family history was more frequent in those with 300T>G BRCA1 gene mutation than in 5382insC carriers." (PMID 22395474, 2012). "In this study, we used immortalized ovarian surface epithelium (IOSE) cells from normal human ovary (IOSE 7576 and IOSE 397) and from an ovarian cancer patient with BRCA1 mutation, IOSE 592F, to investigate the role of BRCA1 in mediating FST secretion in these cells." (PMID 22685544, 2012). "BRCA2-deficient cancer cells are hypersensitive to DNA-crosslinking agents including cisplatin, as a consequence, women with BRCA1/2-mutated ovarian carcinoma have a better diagnosis than those without BRCA1/2- mutation if they receive platinum-based therapy." (PMID 21385444, 2011). "In our study, based on the analysis of a population-based series of unselected breast and ovarian cancer cases in Latvia, we show some aspects of the genotype-phenotype correlation among the BRCA1 c.4034delA (4153delA) and c.5266dupC (5382insC) founder mutation carriers." (PMID 22032251, 2011). "The BRCA1/2 genes account for a significant portion of hereditary breast and ovarian cancers." (PMID 21711529, 2011). "Inherited mutations in the breast cancer susceptibility gene 1 (BRCA1) [MIM 113705] and breast cancer susceptibility gene 2 (BRCA2) [MIM 600185] are associated with a high risk of developing breast and ovarian cancers in females of different age and ethnic groups." (PMID 21559243, 2011). "The aim of this study was to screen seven known BrCa susceptibility genes for additional mutations in 82 well-characterized, Finnish, high-risk hereditary breast and/or ovarian cancer (HBOC) individuals tested to be BRCA1/2-founder mutation negative." (PMID 21356067, 2011). "In the current study, we screened for RAD51C mutations in a clinic-based set of women with breast and/or ovarian cancers in families with HBOC who had previously tested negative for BRCA1 and BRCA2 mutations." (PMID 21980511, 2011). "Also highlighted is the role of BRCA in sporadic breast and ovarian cancer and the emergence of novel targeted therapies such as poly(ADP-ribose) polymerase inhibitors (PARPi) in BRCA1-deficient patients." (PMID 22312502, 2011). "At this time, the NCCN and ACOG guidelines suggest that for patients with BRCA1 or BRCA2 mutations, pelvic ultrasound and CA125 every 6 months may be considered for the detection of early ovarian cancer." (PMID 22312502, 2011).
ovarian carcinoma (continued). "The BRCA1 and BRCA2 mutation spectrum and mutation detection rates according to different family histories were investigated in 521 subjects from 322 unrelated Slovenian cancer families with breast and/or ovarian cancer." (PMID 21232165, 2011). "Breast and ovarian cancer cells lacking function of either the BRCA1 or BRCA2 susceptibility gene products are deficient in homologous recombination and more sensitive to platinum-containing drugs." (PMID 21679440, 2011). "While mutations in BRCA1 are known to significantly increase the chances of developing breast and ovarian cancers, the mechanism behind this predisposition is not fully understood." (PMID 21666281, 2011). "Patients with BRCA1- or BRCA2-linked ovarian cancers were shown to have a longer disease-free interval following chemotherapy and improved survival compared to patients with sporadic ovarian cancer ovarian cancer." (PMID 22312502, 2011). "Finally, many tumors also correlate with defects in DDR factors, for example mutations of either BRCA1 and BRCA2 genes predispose to breast and ovarian cancer." (PMID 21926946, 2011). "Recently, RAD51C, essential for homologous recombination repair, has been reported to be a rare hereditary breast and ovarian cancer susceptibility gene and several pathogenic RAD51C mutations have been identified in BRCA1- and BRCA2-negative hereditary breast and ovarian cancer families (HBOC)." (PMID 21980511, 2011). "A number of clinical trials are currently underway examining the effect of PARPi alone or in combination with platinum agents in ovarian cancers irrespective of BRCA1/2 mutation status." (PMID 20182637, 2010). "It is known that loss of BRCA1 function may ultimately activate JAK-STAT pathways and stimulate cell proliferation in breast, prostate, lung and ovarian cancer." (PMID 20576130, 2010). "In addition, we recently showed that these groups of ovarian carcinoma classified based on BRCA1 status also show near-identical miRNA expression profiles." (PMID 20843305, 2010). "In BRCA1-mutation negative persons the frequency of ovarian cancer was 1.2% (95% CI = 0.6 - 2.5%) and incidence rate - 25.4 (95% CI = 10.2 - 52.4) per 100 thousands." (PMID 21034437, 2010). "Deficiency of BRCA1 and BRCA2 is mainly found in breast and ovarian cancers thus far." (PMID 21108794, 2010). "Clinical trials of PARP1 inhibitors in BRCA1-related and/or triple-negative breast cancers are currently underway to address this hypothesis, and preliminary results in ovarian cancer have been promising." (PMID 24281106, 2010). "This is most likely to suggest a high probability of a BRCA1/2 mutation rather than another mechanism increasing ovarian cancer risk." (PMID 20234365, 2010). "The identification of high penetrance alleles of the BRCA1 (MIM 113705) and BRCA2 (MIM 600185) genes, which determine a high risk of developing hereditary breast and ovarian cancer, has made genetic testing an integral part of oncogenetic counseling in clinical practice." (PMID 24281179, 2010). "There were no ovarian cancer cases in BRCA1 mutation carriers, corresponding to the frequency 0% (95% CI = 0 - 27.8%) and incidence rate 0 (95% CI = 0 - 1213) per 100 thousands." (PMID 21034437, 2010). "In a recent study, members of 283 epithelial ovarian cancer families from the United Kingdom (UK) and the United States (US) were screened for coding sequence changes and large genomic alterations (rearrangements and deletions) in the BRCA1 and BRCA2 genes." (PMID 19536330, 2009).
ovarian carcinoma (continued). "Similarly, in breast and ovarian carcinoma cell lines, BRCA1 and BRCA2 mRNA are concordantly induced by adriamycin, ionizing radiation, and estrogen." (PMID 19602291, 2009). "BRCA1 and BRCA2 are the two tumor suppressor genes associated with breast and ovarian cancer risk." (PMID 19865540, 2009). "Interestingly, we found that promoter methylation only occurs in 15% of those sporadic ovarian carcinomas with low or intermediate BRCA1 expression." (PMID 19602291, 2009). "Recurrent ovarian carcinomas commonly have increased BRCA1 and/or BRCA2 protein expression post chemotherapy exposure which could mediate resistance to platinum based therapies." (PMID 19602291, 2009). "Each of these cases, from the kConFab familial cancer repository, had a family history of breast or ovarian cancer with BRCA1-like breast pathology as defined by kConFab criteria, but were negative for mutations in the coding regions of BRCA1 and BRCA2." (PMID 18269736, 2008). "Mutations in BRCA1 (breast cancer 1, early onset; MIM#113705) and BRCA2 (Breast Cancer Type 2 susceptibility protein; MIM#600185) account for an autosomal dominant transmission of susceptibility to breast and ovarian cancer." (PMID 18489799, 2008). "Ovarian cancers (OC) were more often found in BRCA1 families compared with BRCA2 families." (PMID 18783588, 2008). "With regard to familial cancer phenotype this relatively small cohort does not allow for the uncovering of subtle differences between the BRCA1/2 mutant families, except for the double incidence rate of ovarian cancers in BRCA1 compared to BRCA2 positive families as reported widely before." (PMID 18783588, 2008). "In Spain, a study targeting BRCA1 and BRCA2 mutations in Spanish families with breast/ovarian cancer highlighted a high proportion of variations that appear to be unique to Spaniards, and the existence of recurrent variations associated with the geographical origin of the families." (PMID 18789142, 2008). "The earlier drop in positive:negative ratio for BRCA1 almost certainly represents a higher combined risk of both breast and ovarian cancer to 50 and 60 years." (PMID 18513387, 2008). "Another possible mechanism of c-Fos involvement in tumour suppression could be the direct regulation of BRCA1, a well established factor in familial breast and ovarian cancer." (PMID 18854825, 2008). "On the basis of the evidence for the role of BRCA1 in breast and ovarian cancers, it has been suggested that BRCA1 mRNA expression could also play an important role in predicting differential chemotherapy sensitivity in NSCLC." (PMID 19452042, 2008). "Though sub-classification may be done based on BRCA1 genetic testing, this cannot be done in a timely fashion such that it could be used to guide therapy of patients newly diagnosed with ovarian cancer." (PMID 18208621, 2008). "Germline mutations in BRCA1 and BRCA2 confer a high lifetime risk for breast and/or ovarian cancer, and early studies of familial cancer cases suggested that these risks may be as high as 80%." (PMID 18402691, 2008). "Our data suggest that the PHB 3'UTR polymorphism does not modify ovarian cancer risk in women carrying one of the three Polish BRCA1 founder mutations." (PMID 18397521, 2008). "Penetrance for breast and ovarian cancer by age for BRCA1 and BRCA2." (PMID 18513387, 2008).
ovarian carcinoma (continued). "The role of BRCA1/2 mutations in the Arab population was understudied; therefore the genetic component and the contribution of the BRCA1/2 genes to BC or ovarian cancer (OC) in that population are unknown." (PMID 17233897, 2007). "There are very significant nongenetic effects on breast and ovarian cancer risk in BRCA1 and BRCA2 carriers." (PMID 17213823, 2007). "Data from several international studies suggest that patients with a loss of heterozygosity of the BRCA1 and BRCA2 genes, which are located on 17q21 and found in hereditary forms of breast cancer, have a 6–61-fold increased lifetime risk of ovarian cancer compared with general population rates." (PMID 17211471, 2007). "To investigate whether the increase in chemosensitivity by suppression of BRCA1 expression depends on the cell proliferation, we examined the effect of BRCA1-siRNA transfection on the cell growth of ovarian cancer cell lines." (PMID 19690636, 2007). "There has been one report of an HRAS-linked polymorphism affecting ovarian cancer risk in BRCA1 carriers, but no follow-up studies were published." (PMID 17213823, 2007). "Because the mean age of onset of breast and ovarian cancer is long after menopause, when selection is considered nonexistent, BRCA1 alleles are generally thought to be selectively neutral." (PMID 18030340, 2007). "To address if BRCA1 expression plays a role in the chemotherapeutic response, we analyzed the effect of BRCA1 suppression on the sensitivity to cisplatin and paclitaxel in ovarian cancer cells." (PMID 19690636, 2007). "A BRCA1 or BRCA2 gene mutation is associated with increased risk of breast and/or ovarian cancer." (PMID 17285126, 2007). "As only one case was tested for BRCA1/2 mutation after the diagnosis of ovarian cancer, testing bias did not markedly confound the results (4% change of the SIR, data not shown)." (PMID 17426707, 2007). "BRCA1 is critical in the development of breast and ovarian cancers." (PMID 16928264, 2006). "In one series, approximately 1% of Norwegian women under the age of 70 years with ovarian cancer carried this mutation and it accounts for ~20% of all BRCA1/2 mutation carriers demonstrated by DNA testing today in Norway (Møller, unpublished data)." (PMID 16509964, 2006). "A total of 96 Czech families with recurrent breast and/or ovarian cancer and 55 patients considered to be at high-risk but with no reported family history of cancer were screened for mutations in the BRCA1/2 genes." (PMID 16168118, 2005). "Screening of seven patients with both breast and ovarian cancer and no family history identified one mutation (14.3%) in the BRCA1 gene (c.5266dupC)." (PMID 16168118, 2005). "With the prevalence of aberrations in the expression of TACC3 in the ovarian tumor arrays, we screened the coding sequence of the TACC3 gene in 76 ovarian cancer families that do not have mutations in known ovarian predisposition loci, such as BRCA1 and BRCA2." (PMID 15918899, 2005). "Risk estimates were not markedly different when women with a first primary diagnosis of ovarian cancer were excluded, with a RR (95% CI) for the ≥ 28 CAG cut-point of 0.85 (0.49–1.47) for BRCA1 mutation carriers (P = 0.6), and 1.12 (0.0.55–2.27) for BRCA2 mutation carriers (P = 0.8)." (PMID 15743497, 2005). "Female carriers of a BRCA1/2 genetic mutation, not already affected by cancer, have up to 85 and 60% lifetime risks of developing breast and ovarian cancer, respectively." (PMID 15505627, 2004). "Germline mutations in BRCA1 and BRCA2 predispose to breast and ovarian cancer." (PMID 15353005, 2004). "Since the mapping and the cloning of two genes that confer susceptibility to both breast and ovarian cancer, BRCA1 and BRCA2, it became possible to offer genetic testing to families with a predisposition for breast and/or ovarian cancer." (PMID 15026808, 2004).